OSMR (oncostatin M receptor)
Diseases named in the same sentence as OSMR in open-access papers (continued):
Sharing a sentence is not in itself a finding about the gene and the disease.
bladder cancer (3 papers, 2019 to 2023). "Our study shows a significant association between OSMR gene polymorphism and bladder cancer that potentially impacts tumor grade, recurrence, and overall survival." (PMID 30755233, 2019). "This is a first report of the association between bladder cancer and OSMR gene polymorphisms, to the best of our knowledge." (PMID 30755233, 2019). "Association between the polymorphism of OSMR gene and bladder cancer has been determined, which reveals that OSMR could affect the recurrence rate, overall survival and tumor grade." (PMID 33591944, 2021). "Our study is the first of its kind to report a relationship between the OSMR gene and bladder cancer." (PMID 30755233, 2019). "Furthermore, a recent study performing whole exome sequencing of patients with bladder squamous cell carcinoma, also displayed significantly higher expression of OSM, OSMRβ, and IL-31, suggesting both OSM-OSMR and IL-31-OSMR signaling may impact bladder cancer progression." (PMID 37841259, 2023).
cardiac hypertrophy (3 papers, 2022 to 2024). "By performing loss-of-function animal experiments, we uncovered the detrimental effects of OSMR deficiency on the pathogenesis of cardiac hypertrophy." (PMID 37120549, 2023). "In summary, the present study shows for the first time that OSMR deficiency exerts adverse effects on the development of pressure overload-induced cardiac hypertrophy, which is mediated by OSM/LIFR/STAT3 signalling associated with macrophages and inflammation." (PMID 37120549, 2023). "OSMR deficiency aggravated cardiac hypertrophy, fibrotic remodelling and cardiac dysfunction after AB surgery in mice." (PMID 37120549, 2023). "Based on the in vivo and in vitro data, we concluded that OSMR deficiency could contribute to the development of pressure overload-induced cardiac hypertrophy by modulating macrophage function and the OSM/LIFR/STAT3 signalling pathway." (PMID 37120549, 2023). "To further confirm the relationship between macrophage function and cardiac hypertrophy in OSMR-KO mice, we isolated BMDMs from WT and OSMR-KO mice, and the cells were subsequently used in an adoptive transfer experiment." (PMID 37120549, 2023). "OSMR-knockout (OSMR-KO) mice were subjected to aortic banding (AB) surgery to establish a model of pressure overload-induced cardiac hypertrophy." (PMID 37120549, 2023). "Notably, murine studies have elucidated that the OSMR knockout exacerbates pressure overload-induced cardiac hypertrophy by influencing macrophages and the OSM/LIFR/STAT3 signaling pathway." (PMID 39411310, 2024). "We thus asked whether OSM/LIFR/STAT3 signalling was activated in macrophages and whether it participated in OSMR deletion-regulated cardiac hypertrophy." (PMID 37120549, 2023).
cervical cancer (3 papers, 2020 to 2023). A primary or metastatic malignant neoplasm involving the cervix. "Overall, these results suggest that the OSM–OSMR axis is an important pathway among the IL-6 family in cervical cancer and that OSMR expression levels are significantly associated with a poor prognosis in cervical cancer patients." (PMID 36551576, 2022). "Reanalysis of scRNA-seq data performed in cervical cancer uncovered an interaction between the oncostatin M receptor (OSMR) on tumor cells and OSM induced by tumor-associated macrophages (TAMs)." (PMID 36551576, 2022). "In cervical cancer, overexpression of OSMR is associated with poor clinical outcomes." (PMID 36551576, 2022). "Furthermore, to investigate the association of OSMR expression levels with the prognosis of cervical cancer patients, we analyzed cervical cancer patient data from The Cancer Genome Atlas (TCGA) and found that OSMR overexpression was highly associated with adverse survival rates." (PMID 36551576, 2022). "Among these, 91 genes overlapped with the genes in the EP1 cluster, which consisted of OSMR high-expressing cervical cancer cells that were identified by the scRNA-seq data analysis." (PMID 36551576, 2022). "EGFR, like OSMR, is also known as a biomarker for cervical cancer and induces tumor progression and activation of STAT3." (PMID 36551576, 2022). "Given the heterogeneous characteristics of cervical cancer cells, we next investigated the expression level of the OSMR gene among subgroups of tumor cells." (PMID 36551576, 2022). "This comprehensive transcriptome analysis not only reveals that OSM-STAT3-signaling-related genes contribute to functions of hypoxia, wound healing, and angiogenesis, but also highlights the clinical importance of OSMR-overexpressing cells in cervical cancer." (PMID 36551576, 2022). "Other studies have demonstrated that the oncostatin M receptor (OSMR) is frequently over expressed in cervical cancer and its pro-oncogenic effects are mediated by STAT3 activation." (PMID 32899142, 2020). "More recent work has also evaluated OSMR overexpression utilizing clinical data from the TCGA CESC (cervical cancer) database and found that patients with high OSMR expression display increased expression of mesenchymal makers such as SNAI1, SNAI2 and zinc finger E-box-binding homeobox (ZEB1)." (PMID 37841259, 2023). "Together, these results suggest that a particular cell population with high OSMR expression in heterogeneous cervical cancer cells may be involved in tumor exacerbation with impaired regulation of hypoxia, angiogenesis, wound healing, and cell cycle pathways." (PMID 36551576, 2022). "We then confirmed the expression changes of some of the identified marker genes (OSMR, SNAI1, and HK2) for the cluster in HeLaS3 and SiHa cervical cancer cell lines by RT-qPCR." (PMID 36551576, 2022). "We also found that tumor-progression-related genes were expressed specific to a subpopulation of tumor cells with a high expression of OSMR and that STAT3 activity induced by OSM was inhibited by SD-36, a STAT3 degrader, in cervical cancer cell lines." (PMID 36551576, 2022).
colon cancer (3 papers, 2009 to 2020). "hsa−mir−1249 which was shown to up-regulate genes in colon cancer and was found to be associated with OSMR that affect the progression of colon cancer in stage II in our association study." (PMID 31888617, 2019). "Based on these results, we then examined the methylation frequency of Oncostatin M receptor-β (OSMR) in a larger number of tissue and stool DNA samples collected from colon cancer patients and controls." (PMID 19662090, 2009). "By immunohistochemical staining of a colon normal and cancer tissue microarray with an anti-OSMR antibody, we detected strong expression of OSMR in all non-malignant normal tissues (NN) and adjacent normal colon mucosa (PN) from colon cancer patients." (PMID 19662090, 2009). "Functional studies revealed a suppressive role for OSMR in colon cancer progression." (PMID 19662090, 2009). "A co-expression correlation analysis revealed that STAT/gp130/OSMR/JAK and NF-κB signaling factors are simultaneously expressed in colon cancer." (PMID 32102440, 2020). "Promoter methylation mediated silencing of OSMR in cell lines, and CRC cells with low OSMR expression were resistant to growth inhibition by Oncostatin M. Our data provide a biologic rationale for silencing of OSMR in colon cancer progression and highlight a new therapeutic target in this disease." (PMID 19662090, 2009). "Moreover, OSMR and B4GALT mRNA expression in colon cancer tissues was significantly down-regulated as compared to normal tissues." (PMID 19662090, 2009).
ischemic stroke (3 papers, 2016 to 2023). A stroke disorder caused by obstruction of blood flow to the brain, due to thrombotic (local blood clot formation) or embolic (due to a blood clot or other material traveling from another site) event. "More recently, the complex role of OSM signaling was further demonstrated by the reported neuroprotective activity of OSM against ischemic stroke, which is dependent on neuronal OSMR-β expression and activation, with decreased neuronal OSMR-β expression leading to worse stroke outcomes." (PMID 27287400, 2016). "Furthermore, a recent study showed that overexpression of OSM receptor (OSMR)-β in neurons is protective against ischemic stroke, whereas decreased neuronal OSMR-β expression results in worse stroke outcomes." (PMID 27287400, 2016).
myocarditis (3 papers, 2022 to 2024). Myocarditis is a condition that is characterized by inflammation of the heart muscle (myocardium). "It is reported that the OSMR gene is significantly elevated in septic myocarditis cell models, suggesting its potential role in the progression of sepsis." (PMID 39422492, 2024). "The involvement of OSMR in multiple human heart diseases such as aortic stenosis, myocardial infarction, myocarditis, and various cardiomyopathy makes OSMR a promising new therapeutic target." (PMID 35957694, 2022). "Because OSMR activation has been observed in patients with both inflammatory and non-inflammatory diseases, it is unlikely that OSM release in the myocardium necessarily causes myocardial inflammation per se." (PMID 35163735, 2022). "Its involvement in a variety of human cardiac diseases such as aortic stenosis, myocardial infarction, myocarditis, cardiac sarcoidosis, and various cardiomyopathies make the OSM receptor (OSMR) signaling cascades a promising therapeutic target." (PMID 35163735, 2022).
prurigo nodularis (3 papers, 2021 to 2024). Prurigonodularis (PN) is a skin disease in which hard crusty lumps are formed on the skin that itches intensely. "Fully human monoclonal antibody against OSMR has been generated and is in clinical trials for pruritus in prurigo nodularis." (PMID 39186767, 2024). "In their study, the oncostatin M receptor pathway was believed to be responsible for the pathogenesis of fibrosis in prurigo nodularis." (PMID 37511138, 2023). "In addition, the anti-OSMRβ antibody vixarelimab (KPL-716) is now under a clinical trial for the treatment of prurigo nodularis (ClinicalTrials.gov Identifier: NCT03816891)." (PMID 33924978, 2021).
squamous cell carcinoma (3 papers, 2020 to 2021). A carcinoma arising from squamous epithelial cells. "In squamous cell carcinoma, OSMR overexpression activates cell-autonomous feed-forward signaling that induces further expression of OSMR and OSM, leading to a pro-malignant phenotype." (PMID 32248843, 2020).
acne (2 papers, 2024). An inflammatory process of the sebaceous glands which is characterized by comedones, nodules, papules and/or pustules on the skin. "Moreover, the function of the other genes, including FAS, SDC1, ANGPTL2, IL-15RA, INHBA, and OSMR in lymphocytes, keratinocytes, fibroblasts, and smooth muscle, are yet to be explored, suggesting that acne involves not only the skin’s surface but also a wider systemic dysregulation." (PMID 38854033, 2024).
dilated cardiomyopathy (2 papers, 2025). Cardiomyopathy which is characterized by dilation and contractile dysfunction of the left and right ventricles. "Mice with whole-body deletion of OSMR or cardiomyocyte-specific loss of the gp130 cytokine receptor in cardiomyocytes develop severe dilated cardiomyopathy in response to pressure overload." (PMID 40744288, 2025).
familial medullary thyroid carcinoma (2 papers, 2015 to 2024). An instance of thyroid medullary carcinoma that is caused by an inherited modification of the individual's genome. "Alternatively, RET-p.S891A associated with OSMR gene (p.G513D) variant has been identified in lichen amyloidosis and familial medullary thyroid carcinoma." (PMID 39585007, 2024). "There are no reports on the relationship between familial medullary thyroid carcinoma (FMTC) associated with cutaneous amyloidosis (CA) and RET or OSMR/IL31RA gene mutations." (PMID 26356818, 2015).
hepatocellular carcinoma (2 papers, 2012 to 2024). A malignant tumor that arises from hepatocytes. "In order to characterize the receptor complexes used by rOSM on rat hepatoma cells, we performed RNA interference studies to abrogate the expression of the rat OSMR or blocked the rat LIFR by a LIFR-specific antagonist (LIF-05,)." (PMID 22937020, 2012). "Transfection of JTC-27 rat hepatoma cells with siRNA targeting the rat OSMR resulted in a reduction of OSMR mRNA levels by 80%." (PMID 22937020, 2012). "Moreover, we found downregulation of RNF135 in hepatocellular carcinoma, downregulation of OSMR in colorectal liver metastases and upregulation of HOXC4 in cholangiocarcinoma compared to primary liver cancers and metastatic cancers." (PMID 39766812, 2024). "In order to determine whether the same is true for rOSM, we transfected the murine hepatoma cell line Hepa1c1c7 with siRNA targeting murine OSMR mRNAs." (PMID 22937020, 2012). "Therefore, we first defined the signaling capacities of rOSM on rat hepatoma cells since they express gp130, LIFR and OSMR (data not shown)." (PMID 22937020, 2012).
melanoma (2 papers, 2018 to 2025). A malignant, usually aggressive tumor composed of atypical, neoplastic melanocytes. "For P1, clusters enriched in ER lumen-associated proteins (CIP2A, OSMR, WWTR1), inflammasome-related proteins, and melanoma-specific proteins (CCND1, MITF, MLANA, NOTCH1) were notable." (PMID 40669378, 2025).
metastatic melanoma (2 papers, 2009 to 2013). A melanoma that has spread from its primary site to another anatomic site. "Although the growth of human melanoma cell lines was inhibited by OSM in several studies, metastatic melanoma cell lines lack responsiveness to OSM and this was correlated to the loss of the specific OSMRβ chain." (PMID 24381786, 2013). "Experiments by these investigators showed that histone deacetylase agents enhanced OSMRβ expression and responsiveness of the cell lines, suggesting that epigenetic mechanisms alter the nature of metastatic melanoma in vivo." (PMID 24381786, 2013).
nasal polyp (2 papers, 2023). "We classified the ethmoid sinus mucosa and nasal polyp (NP) samples obtained during surgery into a control group and a CRS group, and we conducted an RT-PCR analysis to determine the mRNA expression levels of OSM and OSMRβ." (PMID 38137445, 2023). "We confirmed the mRNA expression of the IL-6 receptor (comprising IL-6R and gp130 chains) and the type II OSM receptor (comprising OSMR and gp130 chains) but not the type I OSM receptor (comprising LIFR and gp130 chains) in nasal polyp-derived HNECs." (PMID 37047067, 2023).
osteosarcoma (2 papers, 2019). A usually aggressive malignant bone-forming mesenchymal neoplasm, predominantly affecting adolescents and young adults.
prostate carcinoma (2 papers, 2021). A carcinoma that arises from epithelial cells of the prostate gland. "The expression of OSMR could be detected across all cancer types, among which urothelial cancer expressed the highest, while the expression level in prostate cancer was relatively low." (PMID 34702277, 2021). "OSMR promotes proliferation, metastasis, and EMT in prostate cancer." (PMID 34502082, 2021).
Sepsis (2 papers, 2023 to 2024). Sepsis is defined as life-threatening organ dysfunction caused by a dysregulated host response to infection. "This study aimed to determine if the genetic knockout of OSM receptor (OSMR) type II signaling would improve survival in a murine model of sepsis." (PMID 36831019, 2023). "Here, after the induction of sepsis, IL-10 levels were attenuated in OSMR KO mice following the induction of FIP, as were the levels of the pro-inflammatory cytokines IL1β, IL-6, TNF, and KC, which may reflect a more balanced attenuation of inflammation with improved survival." (PMID 36831019, 2023).
Stroke (2 papers, 2016 to 2023). Sudden impairment of blood flow to a part of the brain due to occlusion or rupture of an artery to the brain. "Pan-reactive Osmr regulates the function and survival of neurons recruiting OSMRβ during stroke." (PMID 37270727, 2023).
systemic lupus erythematosus (2 papers, 2018 to 2023). An autoimmune multi-organ disease typically associated with vasculopathy and autoantibody production. "Single nucleotide polymorphisms (SNP) rs22922016 related to OSMR gene has been found to associated to systemic lupus erythematosus (SLE)." (PMID 38022540, 2023).
AIDS (1 paper, 2023). A syndrome resulting from the acquired deficiency of cellular immunity caused by the human immunodeficiency virus (HIV). "Additionally, AIDS-associated KS cells have been shown to express OSMRβ but not LIFRβ or IL-6 receptor, and inhibition of gp130 blocks the growth stimulating effects of OSM in AIDS-KS cells suggesting inhibition of OSM signaling may be beneficial strategy for patients with KS." (PMID 37841259, 2023).
allergic disease (1 paper, 2014). An immune response that occurs following re-exposure to an innocuous antigen, and that requires the presence of existing antibodies against that antigen. "IL-31 signals act through a receptor composed of IL-31 receptor A and oncostatin M receptor promoting the cell activation during allergic diseases." (PMID 25061262, 2014). "IL-31 receptor IL-31RA, oncostatin M receptor, and IL-33 receptor ST2/IL1RL1 are also related with the immunopathological mechanisms of allergic diseases." (PMID 25061262, 2014).
Arthritis (1 paper, 2024). Inflammation of a joint. "Technical advances in special transcriptomics will help us understand the spatiotemporal relationships among OSM+ macrophages, OSMR+ fibroblasts, IL-6+ fibroblasts and IL-6R+ macrophages in the inflamed synovium during the course of arthritis in future." (PMID 39080781, 2024). "Mice specifically lacking OSMR in synovial fibroblasts (Osmr∆Fibro) displayed ameliorated inflammation and joint destruction in arthritis." (PMID 39080781, 2024).
asthma (1 paper, 2016). "We found that faint expression of IL-31RA and OSMR in the controls and there were more positive cells evident in the patients with severe asthma compared with patients with mild asthma." (PMID 26956917, 2016).
Autoimmunity (1 paper, 2018). The occurrence of an immune reaction against the organism's own cells or tissues. "Thereby, it can be concluded that OSMR gene silencing inhibits autoimmunity in CAU mouse models by inactivating the JAK/STAT3 signaling pathway." (PMID 30134804, 2018). "In order to explore a new therapy for CAU, the current study was performed to investigate the possible functioning of the Oncostatin M receptor (OSMR) gene in the autoimmunity of CAU via regulation of the JAK/STAT3 signaling pathway." (PMID 30134804, 2018). "Additionally, the current findings demonstrate that the contents of IL-1, IL-6, IFN-γ and IgE in serum of mice in the OSMR-siRNA group were significantly reduced, indicating that OSMR gene silencing suppressed the autoimmunity of CAU by blocking the JAK/STAT3 signaling pathway." (PMID 30134804, 2018).
brain cancer (1 paper, 2023). A primary or metastatic malignant neoplasm affecting the brain. "Overexpression of OSM and/or OSMRβ is seen more commonly in a multitude of advanced tumors and is linked to decreased patient survival in several cancer types, including breast, cervical, colon, pancreatic, lung, and brain cancer." (PMID 37841259, 2023).
breast tumors (1 paper, 2022). "Our scRNA-seq and FACS analyses revealed that OSM and OSMR have a unique expression pattern in breast tumors, compared with other members of the IL-6 cytokine family." (PMID 35192545, 2022). "Single-cell and bioinformatic analysis of murine and human breast tumors revealed that OSM expression was restricted to myeloid cells, whereas OSMR was detected predominantly in fibroblasts and, to a lower extent, cancer cells." (PMID 35192545, 2022).
central nervous system lymphoma (1 paper, 2023). "OSMR suppresses proliferation in primary central nervous system lymphoma." (PMID 37568720, 2023).